CXCR2 (C-X-C motif chemokine receptor 2)
Diseases named in the same sentence as CXCR2 in open-access papers (continued):
Sharing a sentence is not in itself a finding about the gene and the disease.
colon carcinoma (63 papers, 2004 to 2025). "For examples, the CXCL1/CXCR2 axis has been implicated in colon cancer metastasis and gastric cancer progression." (PMID 37953876, 2023). "Increased expression of CXCL8 and its receptor CXCR2 on tumors and in the tumor microenvironment are associated with increased tumor growth, angiogenesis, and metastatic potential of colon cancer cells (52, –, 54)." (PMID 28717003, 2017). "In the microenvironment of colon cancer, CXCL8 and its receptor CXCR2 can promote the development and metastasis of colon cancer cells." (PMID 40131539, 2025). "In contrast, the CXCR2 axis facilitates integrin-dependent peritoneal metastasis of colon cancer cells." (PMID 41155662, 2025). "In conclusion, our findings offer compelling evidence that S100A8 amplifies the proliferative and invasive properties of colon cancer cells by activating the CXCL5/CXCR2 pathway." (PMID 38817853, 2024). "Previous studies have shown that neutralizing CXCR2 can inhibit neutrophil-mediated colitis; furthermore, genetic knockout of the CXCR2 gene is capable of inhibiting the formation of primary colon cancer in mice." (PMID 39409185, 2024). "The specific receptor for CXCL5 is CXCR2, which is overexpressed in cancers with high metastatic potential, such as breast, lung, and colon cancer cells." (PMID 37015905, 2023). "Another study investigating the role of CXCL2/CXCR2 identified that short hairpin RNA inhibition of CXCL2 reduced the expression of EMT markers in colon cancer cells." (PMID 37509721, 2023). "CXCL1 and its receptor CXCR2 have been reported in colon cancer and gastric cancer and play an important role in metastasis." (PMID 34813418, 2022). "In vitro and mouse-model experiments showed that stimulation with CXCL2 increases the proliferation and adhesion of colon-cancer cells in a CXCR2-dependent manner." (PMID 36230676, 2022). "Mice was laparotomized and injected intraperitoneally with CT-26 colon carcinoma cells and metastatic noduli in the peritoneal cavity was quantified after treatment with a CXCR2 antagonist or integrin-αV-antibody." (PMID 34115261, 2021). "Similar experiments were run in intrahepatic, lung, cholangiocellular, pancreas, kidney, breast and colon cancer samples, also correlating poor disease prognosis to CXCR2 overexpression by cancer cells." (PMID 34038868, 2021). "In conclusion, our results show that CXCR2 and αV integrins on colon cancer cells exert a key function in the formation of peritoneal metastases in vivo." (PMID 34115261, 2021). "Numerous studies have shown that chemokine receptors, such as CXCR2, are expressed on colon cancer cells and has been shown to support hepatic metastasis of colon cancer." (PMID 34115261, 2021). "The role of CXCR2 and αV integrins in the peritoneal dissemination of colon cancer cells remain elusive." (PMID 34115261, 2021). "Our results showed that hsa-mir-4437 was an independent prognostic factor for colon cancer, and CXCR2 was found from the target prediction by both TargetScan and miRDB." (PMID 32582275, 2020). "In analogy to mice with established colon tumors, treatment of Apcfl/fl‐Cdx2CreERT2 mice with combined anti‐Gr1 antibody and CXCR2 inhibitor during and after tumor initiation led to reduced tumor neutrophil infiltration and reduced tumor burden (Fig EV2)." (PMID 31793740, 2020). "Higher expression of CXCR2 in tumor tissues compared to normal tissue has also been reported in the pancreas, lung or colon cancers." (PMID 32727083, 2020). "Accordingly, it has been reported that colon cancers and colon cancer cell lines also abundantly express MIF receptors CXCR2 and CXCR4." (PMID 31557914, 2019). "The overexpression of the CXCL5-specific receptor, CXCR2, has been verified in a variety of tumour cells, including breast, lung and colon cancer cells, and all cancers with a high metastatic index." (PMID 29665837, 2018).
colon carcinoma (continued). "CXCR2 antagonism has also demonstrated significant antitumor activity in a preclinical model for colon cancer and slowed growth and antagonized metastasis in a recombinant mouse model of pancreatic adenocarcinoma." (PMID 28450382, 2017). "It has been reported that blockade of CXCR1 and CXCR2 using SCH 527123 antagonist potentially inhibits human colon cancer liver metastasis and also sensitizes cells to oxaliplatin." (PMID 28484461, 2017). "In human colon carcinoma cell lines, CXCL1 and its receptor CXCR2 have been associated with metastatic potential and are thought to modulate cell proliferation and invasion in both an autocrine and paracrine manner." (PMID 27682863, 2016). "In a preclinical human colon cancer cell growth and metastasis model in nude mice, orally active CXCR2/CXCR1 antagonists partially decreased liver metastasis by reducing tumor neovascularization through CXCR2 signaling." (PMID 26104296, 2015). "MDSCs, particularly granulocytic ones, express CXCR2 and are plentifully present in colonic tumors developed after the combined treatment of AOM and DSS." (PMID 24966464, 2014). "In colorectal cancer, CD133+/CD44+ colon cancer stem cells have a stronger capacity of bone marrow derived mesenchymal stem cells (BM-MSCs) recruitment compared with CD133-/CD44- colon cancer cells due to IL-8/CXCR2 chemotaxis." (PMID 37124519, 2023). "In conclusion, our experimental evidence confirmed that AC may suppress the growth and liver metastasis in colon cancer by regulating EMT via the CXCL8/CXCR2 axis and PI3K/AKT/mTOR signaling pathway." (PMID 35922850, 2022). "Notably, CXCL2-evoked colon cancer cell proliferation and migration were dose-dependently attenuated by co-incubation with the CXCR2 antagonist SB225002 (respectively)." (PMID 34115261, 2021). "Notably, it was observed that CXCL2 was markedly upregulated along the incisional line in mice, which help explain the CXCR2-dependent accumulation of colon cancer cells at the peritoneal wounds." (PMID 34115261, 2021). "Thus, our findings show that accumulation of colon cancer cells at peritoneal wounds is dependent on CXCR2 signaling." (PMID 34115261, 2021). "Interestingly, expression of CXCR1 and CXCR2 has been shown to be elevated in colon tumor epithelium relative to normal adjacent tissue (P < 0.001)." (PMID 30820706, 2019). "Moreover the antitumor effect of LipA in a mouse model of subcutaneous colon cancer was partially decreased by inhibition of neutrophils recruitment using a CXCR2 antagonist, SB225002." (PMID 29983866, 2018). "Moreover, the chemokine receptor CXCR-2 and its ligands CXCL-1 and CXCL-2 have been proposed to facilitate the growth of spontaneous and inflammation-associated colon tumors." (PMID 25890501, 2015). "Additionally, it has been shown that CAFs from colon cancer promote IL8/CXCR2-mediated monocyte adhesion and attraction through upregulation of VCAM-1 expression and IL-6 production, and subsequently promote polarization to an M2 phenotype by expression of CD163 and CD206." (PMID 38606999, 2024). "Moreover, CXCL1 could regulate the infiltration of MDSCs in the premetastatic liver tissue in colon cancer xenografts, while inhibition of its chemokine receptor CXCR2 suppressed the recruitment of MDSCs in the PMN." (PMID 37210553, 2023). "Therefore, hsa-mir-4437 may affect the proliferation and apoptosis of colon cancer cells by targeting CXCR2." (PMID 32582275, 2020). "We discovered that the expression of S100A8 in colon cancer cells led to increased levels of CXCL5 and its corresponding receptor, CXCR2." (PMID 38817853, 2024). "S100A8 facilitates colon cancer cell proliferation, invasion, and metastasis through the CXCL5/CXCR2 biological axis." (PMID 38817853, 2024). "Noteworthy examples include the overexpression of CXCR2 in NK cells targeting renal cell carcinoma and the combined overexpression of CXCR4 and CCR7 for colon cancer." (PMID 39339180, 2024).
colon carcinoma (continued). "We initially measured the mRNA expression levels of ligands for CXCR2 and CCR1 in mouse colon cancer cell lines (MC38, CMT93, CT26 and Colon-26) and a normal rat intestinal cell line (IEC-6)." (PMID 38750114, 2024). "Flow cytometric analysis of surface protein expression on CT-26 cells demonstrated clear-cut expression of CXCR2, CXCR3, CXCR4 and CXCR5, suggesting a potential role of CXC chemokines in colon cancer cell biology." (PMID 34115261, 2021). "Upregulation of IL-8 and its receptor, C-X-C chemokine receptor type 2 (CXCR2), and their autocrine actions are critical factors in promoting the progression and metastasis of colon cancer cells." (PMID 34799554, 2021). "Herein, it was found that the murine colon cancer cell line CT-26 expressed several of the pro-inflammatory chemokine receptors in the CXC chemokine family, including CXCR2, CXCR3 and CXCR4." (PMID 34115261, 2021). "The CXCR2 antagonist, SB225002, dose-dependently decreased CXCL2-induced proliferation and migration of colon cancer cells in vitro." (PMID 34115261, 2021). "VEGFA secreted by colon cancer cells stimulated CXCL1 production by TAMs, which recruited CXCR2+ MDSCs to promote liver metastasis." (PMID 34527668, 2021). "SB225002, an antagonist of CXCR2, reduced Tyr705 phosphorylation of STAT3 and IL‐8 protein expression in HCT116 colon cancer cells, which was also apparent in HCT116 sh‐ZNF143 cells." (PMID 30933430, 2019). "It has been reported that targeting CXCR1 and CXCR2 using orally active small-molecule antagonist, SCH 527123, potentially inhibits human colon cancer liver metastasis and also sensitizes cells to oxaliplatin." (PMID 28484461, 2017). "In colon cancer, MSCs enhance stemness and epithelial–mesenchymal transition through interleukin-8 (IL-8)/CXC chemokine receptor 2 (CXCR2)/mitogen-activated protein kinase (MAPK) and fibroblast growth factor 10 (FGF10)–protein kinase A (PKA)–protein kinase B (Akt)–β-catenin signaling pathways." (PMID 39624211, 2024). "Inhibitor experiments confirmed our hypothesis, validating that S100A8 enhances the proliferation of colon cancer cells and boosts their invasive metastatic potential through the CXCL5/CXCR2 bioaxis pathway." (PMID 38817853, 2024). "Moreover, S100A8 enhances the proliferation and invasion of colon cancer cells, mediated by the chemokine CXCL5 and its receptor CXCR2." (PMID 38817853, 2024). "Taken together, these results suggested that AC may down-regulate CXCL8/CXCR2 chemokine axis and suppressing the PI3K/Akt/mTOR pathway to inhibit the EMT process, thus acting on its anti-liver metastasis effect in colon cancer." (PMID 35922850, 2022). "Moreover, inhibition of CXCR2 dose-dependently decreased CXCL2-triggered migration and proliferation, suggesting that CXCL2 and CXCR2 interactions are operational in murine colon cancer cells." (PMID 34115261, 2021). "In the present study, we observed that administration of the CXCR2 antagonist SB225002 reduced peritoneal metastasis along the incisional wound by 70%, indicating that CXCR2 expressed on colon cancer cells plays an important role in the development of peritoneal surface metastases." (PMID 34115261, 2021). "Moreover, relative study has found that the inhibition of CXCR2 (using inhibitor SCH-527123 and SCH-479833) protects against human colon cancer liver metastasis." (PMID 28415702, 2017). "Others have also shown that CXCR2 and CXCR4 are expressed on the colon cancer cell lines used here." (PMID 24887129, 2014). "In practice, several experimental evidences have documented that high expression of CXCL8 binds to receptors CXCR1 and CXCR2, mediates the transcriptional process of PI3K/Akt/mTOR signaling cascade, and promotes metastasis in multiple malignant tumors, specifically in colon cancer." (PMID 35922850, 2022).
colon carcinoma (continued). "Additionally, Varney’s study reported that orally active CXCR2/1 antagonists (SCH-527123 and SCH-479833) inhibit the human colon cancer liver metastasis mediated in a manner that is mediated by decreased tumour vascularity and increased malignant cell apoptosis." (PMID 29665837, 2018). "Since they targeted the cancer cell rather than immune cells, the mouse colon carcinoma cell line CT26 and human CRC cell line HCT116 confirmed the high expression of CXCR2 in the two cell lines." (PMID 34025668, 2021).
colorectal cancer (59 papers, 2013 to 2026). A primary or metastatic malignant neoplasm that affects the colon or rectum. "Furthermore, in the tumor microenvironment, the role of CXCR2 in ARNT-deficient colorectal cancer mice was evaluated." (PMID 36859266, 2023). "A Phase II Study of the CXCR2 Antagonist Navarixin in Combination with Pembrolizumab for Patients with Advanced Castration-Resistant Prostate Cancer, Microsatellite-Stable Colorectal Cancer, or Non-Small-Cell Lung Cancer." (PMID 41445742, 2025). "YTHDF1 suppresses antitumor immune responses via the m6A–p65–CXCL1/CXCR2 axis, driving colorectal cancer progression and representing a potential therapeutic target for immune checkpoint inhibitor therapy." (PMID 40986143, 2025). "For example, METTL3 has been found to play a role in the progression of colorectal cancer by targeting the m6A-BHLHE41-CXCL1/CXCR2 axis, resulting in the inhibition of antitumor immunity." (PMID 38649363, 2024). "CXCL8 and its receptors (CXCR1, CXCR2, and Duffy antigen receptor for chemokines (DARC)) are associated with the development of colorectal cancer and its liver metastases." (PMID 37142825, 2024). "It has been reported that colorectal cancer cell-derived CXCL1 promotes the secretion of epithelial growth factor (EGF) in an autocrine manner by binding to C-X-C motif chemokine receptor 2 (CXCR2) in colorectal cancer cells." (PMID 38713320, 2024). "Colorectal cancer cell-derived CXCL1 promotes the secretion of epithelial growth factor (EGF) in an autocrine manner by binding to CXCR2 in colorectal cancer cells." (PMID 38713320, 2024). "In the combined treatment of AOM and DSS for the induction of colorectal cancer, a CXCR2-blocking antibody was injected every other week to block the expression of CXCR2, and the growth of mouse colorectal cancer was observed." (PMID 36859266, 2023). "Targeting CXCR2 has been shown to synergize with ICB in multiple preclinical models of KRAS-mutant colorectal cancer and PDAC, providing a potential combination therapy for the treatment of KRAS-mutant patients with cancer in the clinic." (PMID 37581538, 2023). "Arnt−/− mice had significantly more and larger colorectal tumors than WT mice, but blocking CXCR2 with an anti-CXCR2 mAb significantly decreased the incidence of colorectal cancer and delayed the growth of colorectal cancer in mice." (PMID 36859266, 2023). "Different studies have demonstrated that IL-8 and its receptor CXCR2 are two of the most significantly upregulated chemokines in colorectal cancer." (PMID 37174126, 2023). "Unexpectedly, a very recent study (in vitro and in vivo) on colorectal cancer (CRC) demonstrated that activation or recruitment of DCs was impeded by blocking CXCL8-CXCR2 axis with CXCR2 antagonists." (PMID 35011682, 2021). "High levels of CXCL1 and CXCL8 were thought to be responsible for CXCR2+ neutrophil influx in colorectal cancer." (PMID 34503058, 2021). "IRF2 inhibition was found in KRAS-mutated colorectal cancer, contributing to the augmented expression of CXCL3, which binds to CXCR2 on MDSCs to induce migration." (PMID 34689842, 2021). "We reported a novel small RNA sequence, MIRTX, that significantly inhibits KRAS-mutant colorectal cancer cell growth in vitro and in vivo by suppressing NF-kB signaling pathways via direct inhibition of CXCR2 and PIK3R1." (PMID 34834512, 2021). "CXCR2 and CXCL7 overexpression in liver metastases of colorectal cancer was associated with a shorter overall and disease-free survival." (PMID 34503058, 2021). "CXCL8 is secreted by monocytes and macrophages, which exerts potent angiogenic properties on endothelial cells through interaction with CXCL8 receptors CXCR1 and CXCR2 for regulating angiogenesis in colorectal cancer." (PMID 34025668, 2021). "In a study of surgical specimens from patients with colorectal cancer, CXCR2 expression was significantly increased in tumors from patients who had distant metastases in the lung or liver compared to patients with localized disease." (PMID 34944914, 2021).